CAPN6 (calpain 6)
Diseases named in the same sentence as CAPN6 in open-access papers (continued):
Sharing a sentence is not in itself a finding about the gene and the disease.
tumor (10 papers, 2015 to 2025). "Significant change of expression, reaching 10- to 58-fold change between uterine lesion compared to non-tumor counterpart, was observed in CAPN6, CD24, HMGA1, PLAG1, SNORA48, and SNORD10 (upregulation) and DKK3 and STK26 (downregulation)." (PMID 37466765, 2024). "In conclusion, calpain-6 promotes a specific YAP-activity in CSCs and thus prevents death associated with intensive cell division to allow for tumor and metastasis out-growth." (PMID 36153320, 2022). "Our results strengthen previous data showing that calpain-6 expressing CSCs are tumor-initiating cells." (PMID 36153320, 2022). "Knockdown of calpain-6, which is strongly upregulated in cells with tumor-initiating and metastatic capacities, suppressed autophagy as well as hypoxia-dependent prevention of senescence entry." (PMID 30895192, 2019). "CAPN6 is overexpressed in many types of tumor and its function in tumor includes leading to apoptosis resistance, promoting cell proliferation and angiogenesis." (PMID 26375440, 2016). "Furthermore, downregulation of Capn6 promotes tumor cell apoptosis and inhibits angiogenesis, thereby reducing tumor formation." (PMID 39796281, 2025). "Because the mitotic genes code for factors that control mitosis, we hypothesized that the calpain-6/YAP axis plays a crucial role during tumor or metastasis outgrowth by protecting the cells against mitosis-associated cell death." (PMID 36153320, 2022). "Immunohistochemistry of GFP at different times after cell implantation in bone revealed that most of the tumor cells contributing to tumor initiation in the marrow were calpain-6 expressing cells, whereas this specific cell population decreased during tumor progression." (PMID 36153320, 2022). "We speculated that, instead of cleaving protein substrates (including tumor mediators), calpain-6 would interact with VEGFA to promote VEGF secretion, which would enhance angiogenesis." (PMID 31673071, 2019). "A number of fast evolving, placental genes show tumorigenic or tumor suppression activity (ADAM12, ADAMTS18, CAPN6, EGFL6, HTRA4, LIN28B) and others are involved in disorders associated with epithelial and connective tissues (FBN2) or have immune functions (IL1RL1, PRG2, SIGLEC6)." (PMID 26641094, 2015). "In a mouse model for bone sarcoma, knockdown of the nonclassical calpain-6 blocked tumor development, and overexpression of this protease in an osteosarcoma cell line increased autophagic flux, which could rather favor tumorigenesis." (PMID 30895192, 2019).
cancer (8 papers, 2015 to 2025). A tumor composed of atypical neoplastic, often pleomorphic cells that invade other tissues. "It was also found that miR-449a expression was greatly downregulated in cancer tissues of liver compared with that of normal ones and negatively associated with CAPN6 and POU2F1." (PMID 26375440, 2016). "Interestingly, recent findings using calpain-6 regulatory sequence–based reporter assays identified calpain-6 as a target gene for a stemness pathway in embryonic stem and cancer cells." (PMID 31673071, 2019). "Therefore, targeting calpain-6 as a cancer therapy could provide two benefits: inhibition of angiogenesis and prevention of cancer-associated cachexia manifested as muscle atrophy." (PMID 31673071, 2019). "Further research demonstrated that miR-449a inhibited cancer cell proliferation and induced apoptosis via suppressing both POU2F1 and CAPN6." (PMID 26375440, 2016). "Our previous report shows that CAPN6 is regulated by PI3K-Akt pathway and inhibits cancer cell apoptosis." (PMID 26375440, 2016). "The other 6 putative CPAs demonstrated diverse expression profiles, ranging from those found only in a restricted set of cancer types (IGF2BP3, ADAM12), to those overexpressed in most cancer types but also demonstrating elevated expression in normal female reproductive tissues (CAPN6, MMP11)." (PMID 33087697, 2020).
neurodevelopmental disorder (1 paper, 2026). A behavioral and cognitive disorder with onset during the developmental period that involves impaired or aberrant development of intellectual, motor, or social functions. "This work aims to inspire further research into the role of CAPN6 in placental biology and its relevance to neurodevelopmental disorders." (PMID 41683570, 2026). "Although CAPN6 lacks an MIM phenotype code, we hypothesize that it might be enumerated as a novel candidate gene contributing to neurodevelopmental disorders." (PMID 41683570, 2026).
CAPN6 also shares sentences with these, for which no sentence is quoted: neurodegenerative disease (2 papers); Achalasia (1); cervical cancer (1); leiomyosarcoma (1); ovarian carcinoma (1); ovarian tumor (1); Parkinson’s (1); soft (1); soft tissue sarcoma (1); squamous cervical intraepithelial lesions (1).